CDH1 (cadherin 1)
Diseases named in the same sentence as CDH1 in open-access papers (continued):
Sharing a sentence is not in itself a finding about the gene and the disease.
metastatic carcinoma (64 papers, 1995 to 2026). A carcinoma which has spread from the original site of growth to another anatomic site. "For example, the cell–cell adhesion molecule E-cadherin (encoded by CDH1) is a well-known tumor suppressor whose expression is frequently lost in metastatic carcinomas due to promoter CpG island hypermethylation." (PMID 41301491, 2025). "They wield their influence by suppressing specific target genes, notably the E-Cadherin gene (CDH1), thereby underscoring their association with the adverse prognosis observed in metastatic cancer." (PMID 38683136, 2024). "As E-cadherin (CDH1) downregulation in cancer cells often occurs as a result of promoter methylation, loss of promoter methylation at the secondary site causes the metastatic cancer cells to re-express E-cadherin through MET." (PMID 26237148, 2013). "Results revealed a higher Mesenchymal markers in primary cancer cells (e.g., NCAM1, LAMB1, SERPINE1, TCF4, VIM, ZEB1, and ZEB2) and a higher Epithelial markers in metastatic cancer cells (e.g., CDH1, CLDN4, ELF3, EPCAM, KRT18, KRT7, and KRT8)." (PMID 37202394, 2023). "On the other hand, among the up-regulated miRNAs, miR-9 induces EMT by its direct action on CDH1, the E-cadherin gene; and as an oncogenic miRNA, it is upregulated in several primary and in metastatic cancers." (PMID 26681200, 2015). "Gene pathway analysis indicated that HOTAIR-regulated gene sets included CDH1 (E-cadherin) target genes, whose expression is lost in metastatic cancer cells of the mesenchymal phenotype." (PMID 25334066, 2014). "Interestingly, we found that the expression levels of CDH1, which encodes the epithelial marker E-cadherin, CDH5, encoding vascular endothelial cadherin, and the epithelial-to-mesenchymal transition-transcription factor ZEB1, effectively distinguished primary from metastatic cancer cells." (PMID 40332096, 2025).
oral squamous cell carcinoma (64 papers, 2003 to 2026). "Among these genes, mucin 1 (CDH1), also referred to as epithelial cadherin (E-cadherin), is known to promote cell adhesion and has been implicated in the prognostic assessment of oral squamous cell carcinoma using immunohistochemistry." (PMID 37887055, 2023). "IIn oral squamous cell carcinoma, ANLN knockdown increases expression of epithelial markers such as cadherin-1(CDH1) and claudin-1(CLDN1), while reducing mesenchymal markers including vimentin, SNAIL1, and SNAIL2, leading to attenuated EMT." (PMID 41573677, 2025). "Given the significant presence of Fusobacterium nucleatum (F. nucleatum) in oral squamous cell carcinoma (OSCC) lesions, our research aims to explore the intricate interaction between this bacterium and OSCC cells, particularly focusing on the role of E-cadherin (CDH1)." (PMID 38698370, 2024).
esophageal cancer (62 papers, 2011 to 2025). A primary or metastatic malignant neoplasm involving the esophagus. "A similar repertoire as the esophageal cancers is also noted in the cancers of stomach although consisting of a different set of mutated genes (e.g. CDH1, APC, etc.)along with microsatellite instability." (PMID 40720480, 2025). "Decreased expression of CDH1 or CTNNB1 in the cell membranes of cancer cells is associated with poor survival of patients with esophageal cancer." (PMID 27600761, 2016). "Decreased expression of CDH1 is associated with the poor prognosis of patients with esophageal cancer." (PMID 27600761, 2016). "Overexpression of miR-92a restored the metastatic activity of miR-92a, suggesting that miR-92a promoted the migration of esophageal cancer cells by partly inhibiting CDH1." (PMID 35154284, 2022). "Collectively, these findings illustrate the biological importance of CDH1 expression in esophageal cancer metastasis, and further validate the utility of FLO-1 parental and FLO-1LM cells as preclinical models of metastasis." (PMID 27863424, 2016). "E-cadherin/CDH1 is one of the proteins involved in cell adhesion, and it is known that decreased expression of E-cadherin induces lymph node metastasis in esophageal cancer." (PMID 27600761, 2016). "Moreover, CDH1 was confirmed to repress the levels of the matrix metalloproteinase 2 (MMP2) and MMP9 in Esophageal cancer." (PMID 32714095, 2020). "Both CDH1 and CTNNB1 were co-expressed in 22.1 % (19/86) of esophageal cancer tissues." (PMID 27600761, 2016). "Interestingly, the expression of CDH1 may be activated by SOX17, as suggested in esophageal cancer cells." (PMID 38675711, 2024). "While our results suggested that CDH1 or CTNNB1 expression alone did not affect the prognosis of patients, whether CDH1 and CTNNB1 expression may serve as a good prognostic marker in esophageal cancer is still controversial." (PMID 27600761, 2016).
invasive breast carcinoma (57 papers, 2005 to 2025). A carcinoma that infiltrates the breast parenchyma. "In addition, expression of KLF6 and E-cadherin (encoded by CDH1) was significantly downregulated in human invasive breast carcinoma and a significant positive relationship between KLF6 and E-cadherin was observed." (PMID 32733026, 2020). "Approximately 80% of ILCs harbor bi-allelic CDH1 genetic inactivation; however, bi-allelic alterations of this gene are detected in <1% of other forms of invasive breast cancer." (PMID 38347189, 2024). "Twenty (22%) showed evidence for CDH1 gene methylation, and two out of seven lobular invasive breast cancer specimens displayed CDH1 gene methylation." (PMID 36139537, 2022). "The drug panobinostat reversed the M phenotype in invasive breast carcinoma via inducing and upregulating cadherin-1 (CDH1) as a Wnt signaling component." (PMID 35744786, 2022). "We found that expressions of BMP-2 and CD44 were significantly upregulated, whereas expressions of RB1 and CDH1 (E-cadherin) were significantly downregulated in invasive breast cancer." (PMID 28725489, 2017). "For example, hypermethylation of the E-cadherin (CDH1) promoter, and the resultant decrease in its expression, are associated with infiltrating breast cancers." (PMID 18638373, 2008). "This entity, termed lobular-like invasive mammary carcinomas (LLIMCas), is characterized by E-cadherin and p120 immunopositivity and an absence of CDH1 loss-of-function mutations, which are common in classic ILCs." (PMID 41269430, 2025). "In invasive breast cancer, CDH1 is abnormally highly methylated, and E-cadherin expression is markedly downregulated, rendering it more invasive." (PMID 36810560, 2023). "Actually, simultaneous deregulation of miR200cand miR-30c could significantly reduce the survivalrate of breast invasive carcinoma cells via up-regulationof OCT4, SOX2, c-MYC, SNAI1, ZEB1, CDH2 and down-regulation of CDH1 (P=0.02)." (PMID 31376329, 2020). "Actually, deregulation of miR‐204, miR‐200c, miR‐34a, and miR‐10b simultaneously could significantly reduce the survival rate of breast invasive carcinoma via up‐regulation of OCT4, SOX2, KLF4, c‐MYC, NOTCH1, SNAI1, ZEB1, and CDH2 and down‐regulation of CDH1." (PMID 30710426, 2019). "As previously known, CDH1 is highly expressed in ductal invasive breast cancer, but low or absent in lobular invasive breast cancer." (PMID 28392805, 2017).
nasopharyngeal carcinoma (56 papers, 2008 to 2025). A carcinoma arising from the nasopharyngeal epithelium. "In particular, HOTAIR was found to recruit EZH2 to the CDH1 promoter in nasopharyngeal carcinoma (NPC), leading to its transcriptional repression." (PMID 36509828, 2022). "Moreover, IL-8 was shown to increase the methylation of CDH1 gene promoter in nasopharyngeal carcinoma cells by upregulating DNMT1 via the AKT pathway." (PMID 32678024, 2020). "In addition, target genes, such as MMP-9, vimentin (VIM), and CDH1, which were found to be differently expressed in the nasopharyngeal carcinoma cells transfected with miR-10b mimics and with miR-10b inhibitors, were also involved in migration and invasion." (PMID 29262659, 2017). "Additionally, miR-BART9 could also activate β-catenin through CDH1 and promote tumor metastasis in nasopharyngeal carcinoma." (PMID 27801803, 2016).
ductal carcinomas (54 papers, 2005 to 2026). "The UALCAN portal has also demonstrated significantly reduced CDH1 mRNA expression in LBC samples compared to ductal carcinoma, supporting the link between truncating mutations and functional gene silencing." (PMID 40757085, 2025). "In the other hand, somatic CDH1 mutations are detected in 10%–56% of lobular BC and in 5% of ductal carcinomas." (PMID 32886433, 2020). "Although the somatic and germline mutations in CDH1 is restricted to lobular breast tumors, ductal breast carcinomas often show strikingly reduced E-cadherin mRNA and protein expression." (PMID 26285011, 2015). "Similar E-cadherin loss was reported in 85% cases in a series of 71 ductal carcinomas and correlated with promoter methylation of CDH1." (PMID 19751508, 2009). "Invasive lobular BC, but also high-grade ductal carcinomas, show reduced/loss levels of E-cadherin, a calcium-dependent cell–cell adhesion protein and a marker of phenotypic plasticity encoded by the tumor-suppressor gene CDH1." (PMID 39275004, 2024). "Our analysis confirmed that the transcriptional downregulation of CDH1 in ductal carcinomas is weaker than that in lobular ones." (PMID 33808143, 2021). "Several studies have demonstrated that patients with CDH1-mutated LBC have worse long-term survival outcomes compared to patients with ductal carcinoma or lobular tumors without CDH1 alterations." (PMID 40757085, 2025). "Seven differentially expressed genes (KRT5, KRT6 and KRT17 between tumor and normal cells, CDH1, EMP1, DDR1 and DVL1 between lobular and ductal carcinomas) were verified by immunohistochemical detection of proteins on TMA slides comprising of cores from 119 cases." (PMID 17389037, 2007).
endometriosis (54 papers, 2011 to 2025). The growth of functional endometrial tissue in anatomic sites outside the uterine body. "A deeper understanding is required regarding the potential use of CDH1 as a diagnostic marker of endometriosis." (PMID 37047609, 2023). "The molecular mechanisms underlying EMT induced by TWIST in epithelial cells involve functional loss of E-cadherin (CDH1) in the eutopic endometrium of endometriosis patients." (PMID 29937493, 2018). "A heterogeneous profile of the expression levels of the studied genes (BMP-7, SMAD4 and CDH1) and miR-52-3p in the ectopic endometrium with respect to its eutopic counterpart suggests the loss of endometrial epithelium phenotype in women with endometriosis." (PMID 37047609, 2023). "This may also be the reason why relatively few statistically significant results have been obtained with respect to the associations between BMP7, SMAD4, CDH1, and miR-542-3p expression levels and the biochemical parameters and clinical features of endometriosis." (PMID 37047609, 2023). "We have observed, for the first time, reduced THBS expression and CDH1 protein level with the increased metabolic rate of endometriotic epithelial cells under endometriosis-specific PNX-14 stimulation." (PMID 39857742, 2025). "We observed that, in all five algorithms, the expression levels of CDH1 and KRT23 were inversely related to the risk of developing endometriosis." (PMID 40140093, 2025). "The analysis of the expression levels of the tested genes and miR-542-3p according to pain severity showed an insignificant downward trend in the expression levels of CDH1 and miR-542-3p in patients with very severe pain symptoms of endometriosis." (PMID 37047609, 2023). "A novelty of our work was the analysis of miR-542-3p, BMP7, SMAD4, and CDH1 expression in PBMCs obtained from women diagnosed with endometriosis compared to those obtained from healthy women." (PMID 37047609, 2023). "Through IHC, we confirmed that CXCL12 is significantly increased in endometriosis, accompanied by a decrease in the expression E-cadherin (CDH1), which is consistent with bioinformatics analysis." (PMID 32439908, 2020). "We showed a significant inverse expression between TWIST1 and CDH1 in controls and eutopic and ectopic tissue of endometriosis patients." (PMID 26198055, 2015). "We found that TWIST1, SNAIL and SLUG are overexpressed (p < 0.001, p = 0.016 and p < 0.001) in endometriosis, while CDH1 expression was concordantly reduced in these samples (p < 0.001)." (PMID 26198055, 2015). "The analysis of the expression levels of BMP7, SMAD4, CDH1, and miR-542-3p according to the stage of endometriosis demonstrated a statistically significant increase in the level of BMP7 expression in the group of patients with stage III compared to stage IV endometriosis (p = 0.035602)." (PMID 37047609, 2023). "The different patterns of BMP7, SMAD4, and CDH1 gene expression in ECE, EUE, and the control endometrium observed by us suggests the loss of the endometrial epithelium phenotype in women with endometriosis and demonstrates their involvement in the pathogenesis and pathomechanism of this disease." (PMID 37047609, 2023). "Epithelial TWIST1 is overexpressed in endometriosis and may contribute to the formation of endometriotic lesions by inducing epithelial to mesenchymal transition, as CDH1 was reduced in ectopic lesions." (PMID 26198055, 2015). "Various studies have demonstrated the involvement of specific genes, such as E-cadherin (CDH1), p16, PTEN, and PTEN hypermethylation in the promoter region, in promoting the malignant transformation of endometriosis." (PMID 38384812, 2024). "The aim of this study was to evaluate the expression profile of miR-542-3p and the EMT markers (BMP7, SMAD4, CDH1) in matched eutopic endometrium (EUE) and ectopic endometrium (ECE) samples from women with endometriosis in relation to healthy women." (PMID 37047609, 2023).
endometriosis (continued). "A positive correlation was demonstrated between the SMAD4 and CDH1 genes in biopsy material derived from the eutopic endometrium (Rho = 0.681538, p = 0.000176) and in PBMC patients with endometriosis (Rho = 0.526154, p = 0.006900)." (PMID 37047609, 2023). "We further investigated the expression of E-cadherin (CDH1) and CXCL12 in endometriosis or control tissues by IHC." (PMID 32439908, 2020). "IHC confirmed the down-regulation of E-cadherin (CDH1) and up-regulation of CXCL12 in endometriosis tissues." (PMID 32439908, 2020). "The role of EMT and proliferation in the pathogenesis of endometriosis was evaluated by analyzing TWIST1, CDH1 and MYC expression." (PMID 26198055, 2015). "CDH1, TWIST1, SNAIL and SLUG mRNA expression was analyzed by qRT-PCR from 47 controls and 74 patients with endometriosis." (PMID 26198055, 2015). "We did not observe any changes in CDH1 expression under physiological and endometriosis-specific PNX-14 stimulation at the RNA level." (PMID 39857742, 2025). "At the protein level, we observed a strong decrease in the accumulation of CDH1 under stimulation with endometriosis-specific concentrations of PNX-14 (0.05 nM), with no changes in CDH1 under 0.02 nM PNX-14." (PMID 39857742, 2025). "Moreover, we observed a strong negative correlation between the viability of 12Z cells (XTT assay) and the expression of CDH1 and THBS2 in cells treated with PNX-14 at endometriosis-specific concentrations." (PMID 39857742, 2025). "We observed a negative correlation of CDH1 expression levels with pelvic pain symptoms and a positive correlation with the progression of endometriosis, although without statistical significance for either clinical feature of the disease." (PMID 37047609, 2023). "Some authors have reported a negative correlation between CDH1 expression and the presence of deep infiltrative endometriosis." (PMID 37047609, 2023). "BMP7, SMAD4, CDH1, and miR-542-3p expression levels were assessed in PBMCs from endometriosis patients and in PBMCs from patients without endometriosis, who constituted the control group (C2)." (PMID 37047609, 2023). "The study conducted by Li and colleagues has reported the CDH1 promoter methylation in eutopic and ectopic endometrium of women with ovarian endometriosis in 26% and 32% respectively, compared to 8% in the endometrial tissue of women without endometriosis." (PMID 40792071, 2025).
renal cell carcinoma (54 papers, 1995 to 2025). "Therefore, we performed targeted sequencing of CDH1 exons 14 to 16 on tumor DNA of 65 renal cell carcinomas (RCC), the most common type of kidney cancer in adults." (PMID 33929593, 2021). "MALAT1 interacts with EZH2 to suppress E-cadherin (CDH1) expression in renal cell carcinoma." (PMID 26871474, 2016).
invasive carcinoma (52 papers, 1997 to 2025). A carcinoma that is not confined to the epithelium, and has spread to the surrounding stroma. "For instance, expression of CDH1, a major component involved in cell–cell adhesion and frequently negatively associated with metastatic and invasive carcinomas, was enhanced in iAsIII-exposed cells, and expression of its precursor protein, protocadherin 1, was enhanced in DMAIII-exposed cells." (PMID 16507463, 2006). "Evidence suggests that sporadic diffuse gastric cancer may develop from an “alternative” carcinogenetic pathway (i.e., alternative to the dysplasia-invasive carcinoma pathway of Lauren intestinal type) in the context of atrophic/metaplastic gastritis triggered by CDH1 loss of function." (PMID 35925389, 2022). "The legitimacy of this model has been strengthened by the accumulating evidence that down-regulation of the expression of the epithelial marker E-cadherin (CDH1) is a crucial step in the progression from dysplasia to invasive carcinoma." (PMID 31200749, 2019). "However, precursor lesions (pT1a) and/or invasive carcinoma foci are identified in more than 95% of prophylactic gastrectomy in CDH1 carriers." (PMID 37761816, 2023). "The complete loss of CDH1 expression as a single genetic change is not sufficient for the development of invasive carcinoma as shown in animal models where conditional knockout of CDH1 in mice induced SRC but not the development of carcinoma invading into submucosa." (PMID 36869400, 2023). "E-cadherin (CDH1) has successfully separated ductal and lobular invasive carcinomas." (PMID 17389037, 2007).